BRCA1 (BRCA1 DNA repair associated)
Diseases named in the same sentence as BRCA1 in open-access papers (continued):
Sharing a sentence is not in itself a finding about the gene and the disease.
breast cancer (continued). "BRCA1 mutations affect the incidence, progression, diagnosis, treatment, and prognosis of breast cancer throughout the course of the disease." (PMID 35402620, 2022). "Germline mutations in PALB2, ATM, and CHEK2 are also associated with breast cancer risks as high as those associated with BRCA1/2 mutations and are often referred to as BRCA-like breast cancer." (PMID 35884530, 2022). "Regarding clinical impact, the risk of developing basal or Her2 breast cancer was increased 15.7 times or 37.5 times for BRCA1 and MSH6 pathogenic variants respectively." (PMID 35451682, 2022). "BRCA1 suppresses the transcriptional activity meditated by ERα and many breast cancer-associated mutations of BRCA1 abolish or reduce its ability to repress the activity of the receptor." (PMID 36231059, 2022). "PARP inhibitors have shown promising results in the treatment of metastatic breast cancers harboring germline BRCA1/2 mutations." (PMID 35954325, 2022). "Pathological variants of BRCA1 confer a cumulative risk of breast cancer of 40–87% by 70 years of age4,5." (PMID 35393420, 2022). "BRCA1/2 germline mutations are the most frequent germline mutations found in breast cancer and are present in approximately half of all patients with a family history of breast cancer." (PMID 35380032, 2022). "Germline mutation of BRCA1 is very frequent in inherited breast cancer and predisposes women to breast cancer with high lifetime risk 3; In addition, down-regulation of BRCA1 is also observed in sporadic breast cancer." (PMID 35280675, 2022). "BRCA1/2 is an important tumor suppressor gene, with which women take a lifetime risk of breast cancer as high as 85%." (PMID 35311116, 2022). "Patients with breast cancer with BRCA1 or BRCA2 who underwent BCT have a significantly higher risk of a second primary ipsilateral breast event that is almost exclusively a new primary breast cancer rather than a true recurrence." (PMID 36580360, 2022). "Though the study is one of the few studies to date to assess the impact of BRCA1/2 mutations on detailed measures of cardiac function in breast cancer patients receiving anthracyclines, statistical power was limited due to sample size." (PMID 35242827, 2022). "Based on this system, a single-base mutation associated with the breast cancer gene BRCA1 was successfully identified." (PMID 35384520, 2022). "The gene list was used to interrogate TNBC microarray dataset enriched for BRCA1 mutations to identify a subgroup of breast cancers labeled as BRCA1(-)/NF-κB(+) (“NF-κB on”)." (PMID 36531159, 2022). "Both healthy BRCA1/2 gene mutation carriers and women genetically burdened with breast cancer require consultation with a reproductive medicine specialist for individual planning of offspring." (PMID 35887761, 2022). "In a cohort of 3797 BRCA1 mutation carriers diagnosed with breast cancer, 78% had ER-negative breast cancers." (PMID 35118379, 2022). "In our previous work, we reviewed the role of vitamin D in triple-negative and BRCA1-deficient breast cancer cases." (PMID 35328609, 2022). "The HRD-algorithm used in ovarian cancer clinical trials was, however, generated using breast cancer samples or a mixture of breast cancer and ovarian cancer samples using BRCA1/2 mutation as the sole determinant of HRD, and BRCAwt status as HRP8–10." (PMID 36581696, 2022). "In order to identify synthetic lethal partners of EZH2 that are specifically effective in BRCA1-deficient breast cancer, we used BRCA1-deficient and -proficient mammary tumor cell lines to perform a high-throughput drug screen in combination with GSK126." (PMID 35715861, 2022). "Our results revealed a reliable molecular parameter for distinguishing patients with poor prognosis from the BRCA1-mutated breast cancer patients." (PMID 34403063, 2022).
breast cancer (continued). "Cancer cells with harmful mutations in breast cancer susceptibility genes 1 or 2 (BRCA1/2) lack the ability to repair DNA double strand breaks, making these tumors heavily reliant on the single strand break repair pathway." (PMID 36140642, 2022). "In our premenopausal cohort, the frequency of BRCA1 mutations (11.8%) is similar to the prevalence identified in young breast cancer subsets by other investigators." (PMID 36011273, 2022). "Further, we find that some of the Brca1 deficient mammary tumors are CL and that Brca1 deficiency induces basal-like mammary tumors with activation of EMT, which is recently confirmed by an independent group." (PMID 35236825, 2022). "Factors contributing to breast cancer development include strong family history, BRCA1 and breast cancer gene 2 (BRCA2) gene mutations, a history of atypical hyperplasia, alcohol intake, and increased age." (PMID 36358806, 2022). "Since BRCA1-deficient breast cancer is sensitive to PARPi33, 48, future exploration using PARPi for the treatment of these cancers with high DCAF8L1 expression will have important implications." (PMID 35280675, 2022). "This study reveals for the first time that a targetable TGFβR signaling pathway is directly activated by BRCA1-deficiency in the induction of EMT in breast cancer progression." (PMID 35236825, 2022). "Among differentially expressed miRNAs, miR-342-5p (associated with ERα and BRCA1 expression in breast cancer) and miR-1226 were downregulated in tamoxifen-resistant cells." (PMID 36555323, 2022). "The results of double agent treatment in vivo suggest a combination effect by GSK126/AZD1390 treatment and support our in vitro findings of increased sensitivity in BRCA1-deficient mammary tumor cells." (PMID 35715861, 2022). "As deletions overlapping SULT1A1 were suggested to decrease breast cancer risk in BRCA1 pathogenic variant carriers, the relative expression of BRCA1 was quantified to assess if the SULT1A1 knockdown affected its regulation." (PMID 36203093, 2022). "Despite the availability of all these molecular data also for breast cancer, only a few studies have filtered patients according to the presence of BRCA1/2 mutations or the amplification/overexpression of ErbB2." (PMID 35740092, 2022). "When asked about the oncological risk related to BRCA1/2 pathogenic variants, 135 (65.5%) women answered that hormonal contraception increases the risk of breast cancer and 23 (11.2%) that it increases the risk of ovarian cancer." (PMID 35884518, 2022). "Estimated lifetime risk for developing breast cancer in individuals harboring these germline variants is upwards of 72% and 69% for BRCA1 and BRCA2 respectively." (PMID 35685436, 2022). "The probability of developing breast cancer up to the age of 70 for carriers of the BRCA1 gene mutation from North America was estimated at 72% and for carriers from Poland at 49%, indicating the importance of environmental factors." (PMID 35395863, 2022). "hsa-mir-934, as an intronic miRNA of Vestigial-like 1, was found mainly expressed in BRCA1-associated triple-negative basal-like and sporadic breast cancer." (PMID 35887651, 2022). "Our study provides strong evidence that deletions overlapping BRCA1 are associated with a 1.21-fold higher risk of developing breast cancer." (PMID 36203093, 2022). "Individuals with BRCA1/BRCA2 mutations have up to a 70% life‐time risk of developing breast cancer and up to 45% risk of developing ovarian cancer." (PMID 35128817, 2022). "The gene panels include genes with a well-documented association between a rare-monogenic variant and breast cancer (e.g., BRCA1, BRCA2 and PALB2)." (PMID 34755241, 2022).
breast cancer (continued). "PARP inhibitors including olaparib, rucaparib, niraparib, and talazoparib have shown robust efficiency in breast cancer patients with germline BRCA1/2 mutation both as second-line therapy and as first-line therapy." (PMID 35855837, 2022). "Breast cancer-associated genes 1 and 2 (BRCA1 and BRCA2) are tumor suppressor genes encoding a large protein that is involved in many essential biological processes." (PMID 35573021, 2022). "BRCA2‐associated breast cancers are more likely to be hormone receptor positive (HR+) and have lower tumor grade and mitotic counts compared to BRCA1‐associated breast cancers." (PMID 35128817, 2022). "In conclusion, overall survival of BRCA1/2-associated breast cancer patients is better when they are diagnosed with a smaller tumor size within the pT1 category." (PMID 35507134, 2022). "Patients with BRCA1/2 mutated breast cancer generally show an earlier age of onset, on average 5 to 8 years earlier than patients with sporadic breast cancer." (PMID 36439508, 2022). "The expression of MDR1 was found to be low in ovarian carcinomas when BRCA1-deficient mammary tumors were diagnosed initially, whereas the upregulation of this pump protein always occured in parallel with acquired resistance to chemotherapy, including PARPi." (PMID 36253861, 2022). "The development of resistance against PARP inhibitor is being mediated by ABCB1, and it was first reported in BRCA1/2-deficient breast cancer mice models." (PMID 35873570, 2022). "This cancer accounts for 15–20% of all breast cancers and is especially common in patients under 40 years of age, as well as with the occurring BRCA1 mutation." (PMID 36010854, 2022). "MAD2L1 is a component of the mitotic spindle assembly checkpoint that has been linked to early metastasis in breast cancer and is associated with BRCA1/2 pathogenic mutations." (PMID 36860495, 2022). "A strong correlation between the overexpression of DNA helicase genes and HRD was find both in BRCA1/2-mutated breast cancer as well as in BRCA1/2 wild-type breast cancers." (PMID 35855837, 2022). "Using a mouse model for BRCA1-mutated breast cancer, we show here the relevance of LRRC8A- and LRRC8D-mediated cisplatin and carboplatin uptake to kill Pt drug–sensitive tumors." (PMID 36467895, 2022). "Previous studies suggest the magnitude of the breast cancer PRS associations is attenuated in female BRCA1 and BRCA2 carriers compared with associations seen in the general population." (PMID 34320204, 2022). "Breast cancer susceptibility gene one (BRCA1) and two (BRCA2), are well established tumor suppressor genes that play a pivotal role in promoting HR in response to DNA damage." (PMID 36497436, 2022). "Here, we provide a review of the emerging preclinical and epidemiologic evidence implicating the dysregulation of progesterone-mediated receptor activator of nuclear factor κB (RANK) signaling in the pathogenesis of BRCA1-associated breast cancer." (PMID 35418083, 2022). "In breast cancer patients, there were 61.90% (13/21) and 69.57% (16/23) of pathogenic variants were distributed in exon 14 of BRCA1 and exon 11 of BRCA2, respectively." (PMID 35918668, 2022). "Secondly, all cases had a BRCA1 mutation, while two controls had a high risk of developing breast cancer due to a familial predisposition and the other control was identified with a BRCA2 mutation." (PMID 36293255, 2022). "Our current investigation explored the potential prognostic value of CIN in breast cancer patients with germline BRCA1 mutation as well as the possible molecular mechanism." (PMID 34403063, 2022).
breast cancer (continued). "Notable findings were that the cancer progression-associated genes CD44, as well as BRCA1, a classic breast cancer gene, were highly represented in the PPI network for PABC versus NPABC." (PMID 36035177, 2022). "These drugs have shown a great efficacy in the treatment of BRCA1/2-mutated tumors, such as ovarian and breast cancers." (PMID 36555812, 2022). "In breast cancer, cisplatin is of special use for treating tumors that are deficient in BRCA1, since they are hypersensitive to DNA double-strand break (DSB)-inducing compounds." (PMID 36230683, 2022). "According to a meta‐analysis of BRCA1 and BRCA2 carrier families, the lifetime risk of breast cancer varies from 65% to 81% for BRCA1 and 45% to 85% for BRCA2." (PMID 35762299, 2022). "The autosomal dominant conditions most frequently linked to a high risk of breast cancer are hereditary breast and ovarian malignancies brought on by mutations in BRCA1 or BRCA2." (PMID 36140642, 2022). "While actual breast cancer risk differs by study design and case selection, the most comprehensive updated risk estimates are 72% and 69% lifetime risk for BRCA1 and BRCA2 PSV carriers, respectively." (PMID 36349178, 2022). "One such case is associated with breast cancer, in which the deleterious missense mutation c.5242C > A in BRCA1 causes exon 18 skipping, resulting in the loss of 26 aa that are essential for the protein's function." (PMID 35018432, 2022). "Accordingly, cells with impaired HR, for example those harboring pathogenic mutations in breast cancer genes BRCA1 or BRCA2, are hypersensitive to PARP inhibitors and persistently accumulate DSB due to the error-prone NHEJ." (PMID 35456968, 2022). "The aim of the study was the determination of PARP-1 expression in the context of the presence of BRCA1 mutations in circulating tumor cells of breast cancer patients." (PMID 35406503, 2022). "PARP which stands for poly-ADP ribose polymerase, is also a famous target for breast cancer treatment, especially for those who have BRCA-1 and BRCA-2 mutations." (PMID 35927682, 2022). "Carriers of pathogenic variants in BRCA1 have a high risk (approximately > 60%) of developing breast cancer, followed by ovarian cancer (39–58%), and around 5% develop pancreatic cancer." (PMID 36428697, 2022). "To identify the molecular determinants for activation of EMT in Brca1 deficient mammary tumors in an unbiased manner, we performed microarray analysis." (PMID 35236825, 2022). "For example, loss of 53BP1 or components of the non‐homologous end‐joining pathway can suppress the synthetic lethal interaction between poly (ADP‐ribose) polymerase 1 (PARP1) and the breast cancer susceptibility gene BRCA1." (PMID 34706158, 2022). "The genes most commonly affected in hereditary breast cancer and ovarian cancer are breast cancer susceptibility genes 1 and 2 (BRCA1/2)." (PMID 36358816, 2022). "Breast cancer patients with GPVs in BRCA1/2 and other breast cancer-associated genes benefit from particular patterns of systemic treatments and risk-reducing interventions." (PMID 35209950, 2022).
breast cancer (continued). "Pathogenic variants in the BRCA 1/2 genes represent a significant risk factor for cancer development, with a lifetime cumulative risk up to 72–69% for breast cancer and 44–17% for ovarian cancer for BRCA1 and BRCA2 pathogenic variant carriers, respectively." (PMID 35884518, 2022). "A score was generated by transcriptomic profiling using gene set variation analysis algorithm on 34 BRCA1-mutation related genes selected by high AUC levels in ROC curve between BRCA1 mutation and wildtype breast cancer." (PMID 36371386, 2022). "For instance, BRCA1 DNA repair associated (BRCA1), a breast cancer susceptibility gene, is involved in lobular-alveolar development in the mammary gland." (PMID 35049829, 2022). "It has been established that breast cancer development has genetic undertones with breast cancer susceptibility genes 1 and 2 (BRCA1 and BRCA2) as the most famous." (PMID 36942145, 2022). "Here we show that functional analysis of a candidate modifier gene using a model cell line is able to provide additional evidence that SULT1A1 deletions lead to reduced risk of breast cancer in BRCA1 pathogenic variant carriers." (PMID 36203093, 2022). "Our study also found that 12 (9.8%) BBC patients carried BRCA2 deleterious variants, higher than eight (6.5%) identified with BRCA1 deleterious variants, which was similar to other Chinese studies that evaluated unselected breast cancer patients." (PMID 36324133, 2022). "The association with bilateral breast cancer reflects an increased risk of developing contralateral BC in carriers of PV/LPV in BRCA1/2 genes." (PMID 36329109, 2022). "Previously, several studies compared OS or breast cancer-specific survival (BCSS) between BRCA1/2-associated and sporadic BC." (PMID 35507134, 2022). "Risk-reducing mastectomy (RRM) is the most efficient form of breast cancer (BC) risk reduction in BRCA1/2 pathogenic variant (pV) carriers." (PMID 36011268, 2022). "Pathogenic variants (PV) in known breast cancer (BC)-associated genes have been explored since the identification of the BRCA1 risk variant in 1994." (PMID 35938029, 2022). "The women carriers of pathogenic variants (mutations) in the BRCA1 and BRCA2 genes (BRCA1/2) show a very high risk of breast cancer (BC) and/or ovarian cancer (OC)." (PMID 35356420, 2022). "Women carrying a pathogenic germline BRCA1 or BRCA2 mutation have life-time breast cancer (BC) risks up to 75%, and are often diagnosed with BC at a relatively young age." (PMID 35507134, 2022). "For example, in genetically modified models of BRCA1/2-deficient mice for breast carcinoma, depletion of PARG leads to the development of resistance to PARP inhibitor drugs." (PMID 35873570, 2022). "Deleterious variants in DNA damage response genes, mainly in lung cancer, are associated with a higher mutational burden, as observed in breast carcinomas with DNA damage repair gene variants and in our tumor samples with BRCA1, BRCA2, and PALB2 variants." (PMID 35875117, 2022). "Just 3% of BC patients have genetic alterations in the Breast Cancer Type 1 susceptibility (BRCA1) gene, yet BRCA1 mutation carriers have a 70% lifetime risk of developing breast cancer." (PMID 36333737, 2022). "In the BRCA1 gene, we identified 18 variants (4 in both patient groups (ovarian and breast cancer patients), 1 mutation variant in the BC patient group, and 13 mutation variants in the ovarian cancer patient group)." (PMID 35409996, 2022). "The concept of the ‘BRCAness’ phenotype implies the properties that some sporadic breast cancers (BC) share with BRCA1/2-mutation carriers with hereditary BC." (PMID 35715772, 2022). "Carrying a pathogenic BRCA1/2 variant increases greatly young women’s risk of developing breast cancer (BC)." (PMID 35858847, 2022). "Since a major characteristic of BRCA1-mutated breast cancer is an overabundance of small TDs, we here describe a method to identify transcripts with TDs using RNAseq and applied this method to a large cohort of BC samples." (PMID 35159019, 2022).